FEZ1 (fasciculation and elongation protein zeta 1)
Description:
May be involved in axonal outgrowth as component of the network of molecules that regulate cellular morphology and axon guidance machinery. Able to restore partial locomotion and axonal fasciculation to C.elegans unc-76 mutants in germline transformation experiments. May participate in the transport of mitochondria and other cargos along microtubules.
Synonyms: UNC-76; STT3A-AS1
Tractability: Antibody: UniProt places it where antibodies can reach, with medium confidence; its Gene Ontology location is reachable by antibodies, with medium confidence. PROTAC: UniProt records ubiquitination sites on it.
Gene: Protein-coding gene on chromosome 11 (125,442,881 to 125,592,578, reverse strand). Ensembl gene ENSG00000149557.
Subcellular location: Cytoplasm, cytoskeleton, microtubule organizing center, centrosome; Cell membrane
Subcellular location (Human Protein Atlas): Cytosol; Microtubules
Gene Ontology:
Molecular function: protein binding; gamma-tubulin binding; protein kinase C binding
Biological process: negative regulation of autophagosome assembly; axon guidance; cell adhesion; nervous system development; cellular response to growth factor stimulus; establishment of cell polarity; establishment of mitochondrion localization; hippocampus development; mitochondrion organization; positive regulation of anterograde axonal transport of mitochondrion; positive regulation of neuron projection development
Cellular component: Golgi apparatus; axon; cytoplasm; centrosome; dendrite; growth cone; neuronal cell body; plasma membrane
Genetic constraint (gnomAD): Loss-of-function variants: 13 observed, 31.42 expected, observed/expected ratio (o/e) 0.41, 90% interval 0.27 to 0.66. The upper end of that interval is the gene's LOEUF score, 0.66, which puts it in group 2 of 6, group 1 being the genes least tolerant of losing a copy. Missense variants: 298 observed, 363.03 expected, observed/expected ratio (o/e) 0.82, 90% interval 0.75 to 0.9. Synonymous variants: 118 observed, 141.27 expected, observed/expected ratio (o/e) 0.84, 90% interval 0.72 to 0.97.
Homologues: Orthologues: chimpanzee FEZ1 (100% identical), macaque FEZ1 (99% identical), rabbit FEZ1 (98% identical), pig FEZ1 (97% identical), guinea pig FEZ1 (97% identical), rat Fez1 (96% identical), mouse Fez1 (95% identical), dog FEZ1 (88% identical), tropical clawed frog fez1 (79% identical), zebrafish fez1 (70% identical), Drosophila melanogaster Unc-76 (32% identical), Caenorhabditis elegans unc-76 (28% identical). Paralogues in human: FEZ2 (42% identical).
Diseases named in the same sentence as FEZ1 in open-access papers:
FEZ1 is named in the same sentence as 32 diseases in open-access papers, as found by Europe PMC text mining. Sharing a sentence is not in itself a finding about the gene and the disease. The quoted sentences say what the papers report.
schizophrenia (17 papers, 2009 to 2023). A major psychotic disorder characterized by abnormalities in the perception or expression of reality. "Gene association and other studies have identified FEZ1 as being directly, or indirectly, implicated in schizophrenia susceptibility." (PMID 37746155, 2023). "We found that neurexin 1 (NXRN1) expression, a high probability susceptibility gene for schizophrenia was particularly tightly coupled to FEZ1 expression across our samples." (PMID 37746155, 2023). "FEZ1 is known to directly bind to DISC1 (disrupted in schizophrenia 1) protein, an important SZ risk, to regulate neurite outgrowth." (PMID 33446247, 2021). "The results of this study demonstrate that Hdac11 knockout mice provide a means to examine the functional association between HDAC11 and schizophrenia-associated FEZ1." (PMID 28928414, 2017). "Together, our results reveal an OL-specific mechanism for regulating FEZ1 expression at transcriptional and post-transcriptional levels; both are susceptible to dysregulation in schizophrenia." (PMID 29249816, 2017). "Given previous associations between HDAC11, FEZ1 and schizophrenia, a goal of future research should be to examine the performance of homozygous Hdac11 knockout mice in behavioural tests." (PMID 28928414, 2017). "This suggests that HDAC11 has an age-dependent, brain region specific function in regulating FEZ1, a gene associated with schizophrenia." (PMID 28928414, 2017). "FEZ1 has been associated with the dendritic growth of neurons and risk of schizophrenia via its interaction with DISC1 (disrupted in schizophrenia 1)." (PMID 28928414, 2017). "In this study, we investigated the function and regulation of the well-recognized schizophrenia risk factor, Fasciculation and Elongation Protein Zeta-1 (FEZ1), in OL." (PMID 29249816, 2017). "The Fasciculation and Elongation Protein Zeta-1 (FEZ1) is a well-recognized schizophrenia risk factor." (PMID 29249816, 2017). "At the post-transcriptional level, the selective RNA-binding protein QKI, a glia-specific risk factor of schizophrenia, binds FEZ1 mRNA." (PMID 29249816, 2017). "Mice deficient in fasciculation and elongation protein zeta 1 (Fez1) displayed a schizophrenia-like hypersensitivity to psychostimulants and antidepressant-like reduced immobility in the FST." (PMID 25762938, 2015). "Through expression data and polymorphisms, FEZ1 has been related to the etiology of schizophrenia and also interacts with the DISC1 protein - one of the most studied genes in this disease." (PMID 24116125, 2013). "Genetic association studies in cohorts of schizophrenia patients further revealed an epistatic interaction between FEZ1 and DISC1 for risk of schizophrenia." (PMID 22891052, 2012). "In addition, HDAC11 is a schizophrenia susceptibility gene knock down of which has been demonstrated to downregulate expression of FEZ1." (PMID 37746155, 2023). "FEZ1 is a neurodevelopmental gene, which has been associated with schizophrenia." (PMID 34324492, 2021). "Moreover, the Fasciculation and Elongation Protein Zeta-1 (FEZ1) is another myelin-related gene associated with risk for schizophrenia." (PMID 32425837, 2020). "FEZ1 has also been found reduced in the hippocampus of patients with schizophrenia and its expression has been associated with disrupted regulation of transcription factors and altered (epi)genetic regulation, including histone acetylation and chromatin remodeling." (PMID 32425837, 2020). "However, in differentiating neural cells we observed decreased expression of schizophrenia-associated gene Fez1 (fasciculation and elongation protein zeta 1), a gene previously reported to be regulated by HDAC11 activity." (PMID 28928414, 2017). "Furthermore, from the analysis of tissue specific eQTL (GTEx) and GWAS association data, we found that decreased expression levels of FEZ1, a well-recognized risk factor for schizophrenia also involved in neuronal development, neuropathology, and viral infections, increases the risk for BD." (PMID 36303132, 2022).
schizophrenia (continued). "Thus, malfunction of different factor(s) can converge on FEZ1 deficiency in schizophrenia." (PMID 29249816, 2017). "The report of reduced FEZ1 gene expression in the hippocampus of patients with schizophrenia is particularly relevant as this was seen in the homozygous Hdac11 knockout mice." (PMID 28928414, 2017). "Human genetic studies and expression studies have associated PDE4B, FEZ1, SRR, and KALRN with schizophrenia." (PMID 25762938, 2015). "Among these, FEZ1 was recently shown to interact with DISC1, a susceptibility gene for schizophrenia and other mental disorders." (PMID 24063311, 2013). "Moreover, we identified a molecular orchestra that controls FEZ1 expression in OL by sophisticated transcriptional and post-transcriptional mechanisms, which contain multiple factors dysregulated in schizophrenia." (PMID 29249816, 2017). "Genetic alterations in the FEZ1 gene are found in schizophrenia patients." (PMID 29249816, 2017). "We further showed that transcription of the Fez1 gene in OL cells is governed by a sophisticated functional interplay between histone acetylation-mediated chromatin modification and transcription factors that are dysregulated in schizophrenia." (PMID 29249816, 2017). "In order to confirm the specificity of sox11 mediated reduction in caspase-6 activity, we co-transfected caspase-6 with two other proteins, FEZ1 which was identified from the yeast-two hybrid screen and DISC1 which is a known susceptibility protein for Schizophrenia." (PMID 26505998, 2015). "Indeed DISC1, neuregulin, ERBB4, FEZ1 or COMT knockout mice display many of the pathological and behavioural symptoms associated with schizophrenia." (PMID 22567321, 2011). "Furthermore, our study decodes the coordination of multiple schizophrenia-affected genes that converge on regulation of FEZ1 in OL, offering a model to explain how malfunction of distinct risk factors can lead to common abnormalities in the pathogenesis of psychiatric disorders." (PMID 29249816, 2017). "However, whether FEZ1 is expressed in OL cells and FEZ1 deficiency contributes to OL impairment in schizophrenia has not been investigated." (PMID 29249816, 2017). "FEZ1 was recently shown to interact with DISC1, a known candidate gene for both autism and schizophrenia." (PMID 24063311, 2013). "Seven genes, APP, ERBB3, FEZ1, HSPA2, SERPINI1, SOX10 and SYN2, display altered expression in studies of schizophrenia or bipolar disorder." (PMID 19300510, 2009).
breast carcinoma (8 papers, 2004 to 2024). "FEZ1 is silenced in association with promoter methylation in various malignancies, including gastric and breast cancer." (PMID 29435136, 2018). "Furthermore, LOH at the chromosomal region where the FEZ1 gene lies (8p21-22) has been also associated with the invasive behavior of breast cancer and with prostate cancer progression." (PMID 15357873, 2004). "Among these, FEZ1 appeared to exert the most substantial influence on breast cancer OS, manifesting a hazard ratio (HR) of 1.87 (95% CI: 1.18–2.97, p = 0.007)." (PMID 38756447, 2024). "FEZ1 suppresses prostate, esophageal, gastric, bladder, and breast cancer progression, and mediates promoter methylation-mediated transcriptional downregulation and mitosis inhibition." (PMID 35060926, 2022). "The results revealed a notable downregulation of AVPR1A, FEZ1, HGF, GSN, NEDD9, and EGR3 expression in the breast cancer cell lines (MCF7, BT-474, SK-BR-3, MDA-MB-231) when compared to the normal mammary epithelial cell line (MCF-10A)." (PMID 38756447, 2024). "We show that Star-PAP and PIPKIα together regulate 3′-end processing and expression of pre-mRNAs encoding key anti-invasive factors (KISS1R, CDH1, NME1, CDH13, FEZ1, and WIF1) in breast cancer." (PMID 29203642, 2018).
Alzheimer disease (3 papers, 2016 to 2025). A progressive, neurodegenerative disease characterized by loss of function and death of nerve cells in several areas of the brain leading to loss of cognitive function such as memory and language. "Interestingly, abnormal co-aggregates of FEZ1 and Kinesin-1 were described in the brains of mouse models of Alzheimer’s disease, suggesting a perturbation of FEZ1-mediated synaptic protein delivery." (PMID 33071754, 2020). "Strikingly, abnormal co-aggregates of unphosphorylated FEZ1, Kinesin-1 and its putative cargoes are present in brains of transgenic mice modelling aspects of Alzheimer’s disease, a neurodegenerative disorder exhibiting impaired axonal transport and altered MARK activity." (PMID 27247180, 2016). "In this study, we report that FEZ1, a Kinesin-1 adapter involved in neuronal development and axonal transport, is associated with cargoes enriched for presynaptic functions and is regulated by MARK/Par-1, a kinase implicated in the pathogenesis of Alzheimer’s disease." (PMID 27247180, 2016). "Taken together, these results provide mechanistic insights into FEZ1’s roles in neuronal development and synaptic function and suggest that impaired delivery of proteins to synapses via a FEZ1-mediated transport route potentially contributes to the pathogenesis observed during Alzheimer’s disease." (PMID 27247180, 2016).
lung carcinoma (3 papers, 2007 to 2025). "FEZ1 is supposed to be a tumor suppressor in several cancer entities including bladder, breast or lung cancer." (PMID 31717802, 2019). "Meanwhile, the mortality rate of lung cancer patients with high FEZ1 expression has declined." (PMID 40746884, 2025). "Alterations of these genes may occur as an early event in the development of cancer, and their association with metastasis is not confirmed even though one very recent study indicated that FEZ1 may serve as a novel prognostic indicator for lung cancer." (PMID 17784942, 2007).
mental disorder (3 papers, 2013 to 2022). A disease that has its basis in the disruption of mental process. "The sophisticated regulatory pathways that secure the abundance of FEZ1 in OL contain numerous risk factors affected in psychiatric diseases." (PMID 29249816, 2017). "In this regard, genetic alterations that result in FEZ1 deficiency and/or malfunction will affect not only neurons but also OL lineage cells, which contribute to the OL etiology in psychiatric diseases." (PMID 29249816, 2017). "FEZ1 gene mutations or protein structure changes may make individuals susceptible to mental disorders and cognitive disorders." (PMID 35435132, 2022). "This raises an intriguing possibility that aberrant histone acetylation, perhaps due to malfunction of HDACs, may selectively affect multiple key players in OL development beyond FEZ1, which underlies OL-specific etiology of mental illnesses." (PMID 29249816, 2017). "From these evidences, the role of FEZ1 in mental illness and emotional cognitive impairment cannot be ignored." (PMID 35435132, 2022). "Interestingly, a number of repressor TFs predicted to bind Fez1 promoter are aberrantly increased in brains of mental illness, whereas activators TFs for FEZ1 are reduced, similar to the effects in OL upon TSA treatment." (PMID 29249816, 2017). "Besides connecting FEZ1 with TFs that are dysregulated in psychiatric disorders, our studies also identified FEZ1 as a downstream target of QKI-dependent post-transcriptional regulation, which is essential for OL differentiation and myelinogenesis." (PMID 29249816, 2017).
viral infection (3 papers, 2010 to 2022). "The findings reported so far indicate that FEZ1 is associated with neuronal development, neuropathologies, and viral infection." (PMID 20730382, 2010). "Approximately 80% of endogenous FEZ1 protein was eliminated 6 d post virus infection (DPI)." (PMID 33771901, 2021).
colorectal cancer (2 papers, 2018 to 2021). A primary or metastatic malignant neoplasm that affects the colon or rectum. "Supporting this, FEZ1 colocalizes with VAMP2 in developing hippocampal neurons and forms a separate complex with deleted in colorectal cancer (DCC) and Syntaxin-1 (Stx1), components of the Netrin-1 signaling pathway that are also involved in regulating axon and dendrite development." (PMID 33771901, 2021).
leukaemia (2 papers, 2019 to 2021). "But interestingly in leukemia, dysregulated FEZ1 might have opposing effects." (PMID 31717802, 2019). "Overexpression of FEZ1 in HEK293 and HeLa cells resulted in multi-lobulated nuclei as often observed in human leukemia cells." (PMID 31717802, 2019). "The top 10 upregulated genes such as FEZ1 and PDK4 are reported with proto‐leukaemia effects." (PMID 34432355, 2021).
acute myeloid leukemia (1 paper, 2018). Acute myeloid leukemia (AML) is a group of neoplasms arising from precursor cells committed to the myeloid cell-line differentiation. "More surprisingly, HOXB4 was reported to correlate with acute myeloid leukemia 21, which is very consistent with our findings regarding FEZ1 expression in this disease (not published)." (PMID 29321952, 2018).
Anxiety (1 paper, 2021). Intense feelings of nervousness, tension, or panic often arise in response to interpersonal stresses. "Other genes previously linked to mood, anxiety, or trauma-related disorders included protein zeta-1 (FEZ1), ADCYAP1, BRSK2, catenin alpha 3 (CTNNA3), and par-3 family cell polarity regulator (PARD3)." (PMID 34799556, 2021).
cerebellar tumor (1 paper, 2011). "But here in malignant glioma, human cerebellar tumor and primitive neuroectodermal tumor (PNET) the expression of FEZ1 is increased signifying a failed attempt of the cell to contain the tumor growth." (PMID 21909426, 2011).
depression (1 paper, 2022). "At present, there is no research on has-miR-129-5p on post-stroke depression, but our previous experiments found that post-stroke depression was significantly reduced, while FEZ1 protein was significantly increased." (PMID 35435132, 2022). "Analyzing the protein regulatory network of FEZ1, in a series of interaction proteins obtained, it is found that the three autophagy-related proteins SCOC, ULK1, and NBR1 might play a role in depression." (PMID 35435132, 2022).
gastric carcinoma (1 paper, 2004). A carcinoma that arises from epithelial cells of the stomach. "Mutations of FEZ1 gene have been reported in several solid tumors, including prostate, breast, esophageal, and gastric carcinomas." (PMID 15357873, 2004).
HIV-1 infection (1 paper, 2019). The type species of lentivirus and the etiologic agent of acquired immunodeficiency syndrome (AIDS). "The interaction between FEZ1 and kinesin-1 was shown to be important for the ability of FEZ1 to promote HIV-1 infection, suggesting that FEZ1 mediates kinesin-1-dependent HIV-1 inward trafficking along microtubules." (PMID 31028522, 2019).
liver cancer (1 paper, 2023). An epithelial or non-epithelial malignant neoplasm that arises from the liver. "PLK3, C9orf72, TRIM22, RNF152, FEZ1 and MEFV were dramatically downregulated in liver cancer patients, but upregulated by CTD treatment in HCC cells." (PMID 38017425, 2023).
lymph node metastases (1 paper, 2004). "Statistical analysis showed a statistical trend (P = 0.06) between loss and reduction of Fez1 and presence of lymph node metastases." (PMID 15357873, 2004). "In our study, we found loss of Fez1 expression in the majority of CDCs studied and a correlation with the presence of lymph node metastasis." (PMID 15357873, 2004). "Loss and reduction of Fez1 were correlated with a higher prevalence of lymph node metastases (71% vs. 0%, p = 0.061), although the same was not true for distant metastases or tumor stage." (PMID 15357873, 2004).
renal carcinoma (1 paper, 2004). A carcinoma arising from the epithelium of the renal parenchyma or the renal pelvis.
transitional cell carcinoma of the bladder (1 paper, 2004). "In addition, reduced Fez1 expression is associated with high-grade transitional cell carcinoma of the bladder." (PMID 15357873, 2004).